TGFBR2 (transforming growth factor beta receptor 2)
Diseases named in the same sentence as TGFBR2 in open-access papers (continued):
Sharing a sentence is not in itself a finding about the gene and the disease.
tumor (continued). "Finally, the MSI- and/or TGFBR2-dependent proteome of serum exosomes of MSI tumor patients could serve as a novel source of MSI-specific diagnostic markers." (PMID 28376875, 2017). "Furthermore, GSDMC promoted tumor cell proliferation in colorectal carcinogenesis and may be a promising therapeutic target for patients with CRC having TGFBR2 mutations." (PMID 27835699, 2016). "Moreover, GSDMC was upregulated by TGFBR2 mutation in CRC and promoted tumor cell proliferation in CRC carcinogenesis, suggesting that GSDMC may be a promising therapeutic target." (PMID 27835699, 2016). "Furthermore, multivariate Cox regression model using tumor stage, Gleason≥ 8, and PSA levels at diagnosis as covariants, demonstrated a higher risk of earlier relapse in TGFBR2-875GG PC patients following ADT (hazard ratio- HR= 1.47, 95%CI: 1.05-2.05, P= 0.024)." (PMID 23951322, 2013). "In the cases of TGFBR2 and ACVR2, instances of somatic homozygous mutation affecting non-repetitive coding sequences are reported also in non-MSI tumors, those exhibiting chromosomal instability (CIN), strengthening the argument for a tumor-suppressive role for these genes." (PMID 16417627, 2006). "Critically, the immunosuppressive phenotype of TGFBR2High mGSCs is blocked by TGFBR2 inhibition, decreasing CD8+ T cell exhaustion and restoring CD4+ and CD8+ T cell tumor cell-killing ability in vitro." (PMID 40277917, 2025). "We knocked down Tgfbr2 on Kras mutant LUAD cell line (LKR) by in vitro and found high expression of TGFβ1 in tumour cells and supernatant." (PMID 41431249, 2025). "The most frequently affected genes are different by tumor type, conferring selective advantages in CRC (e.g., TGFBR2, ACVR2A, BAX) versus EC (e.g., JAK1, TFAM)." (PMID 41463230, 2025). "TGFBR2 was connected to TGF-β and Th17 differentiation pathways, linking NKT activity with immune modulation and tumour suppression." (PMID 41301032, 2025). "Together, the findings suggest that myeloid Tgfbr2 deletion enhances CD103+ DCs function and activates CD4+ and CD8+ T cells leading to an IFN-γ rich tumor microenvironment." (PMID 40568095, 2025). "Examination of differentially-expressed genes comparing Tgfbr2MyeKO dormant tumor cells vs. those from the control mice suggested that dormancy may arise from signals within an activated immune microenvironment dependent on myeloid-specific Tgfbr2 deletion (red arrows)." (PMID 40568095, 2025). "In a Tgfbr2-KO-to-distant-Jak2-KO task, kNN yields flat Plac8 predictions, whereas CONCERT reconstructs high Plac8 in the tumor core and low Plac8 at the surface, recovering the ground-truth spatial pattern." (PMID 41292874, 2025). "TGFBR2-engineered CAR-T cells exhibited superior survival and proliferation and generated sustained anti-tumor efficacy in tumor xenograft mouse models." (PMID 38918817, 2024). "High expression of TGFBR2 in dominant NK cells of SCLC impairs their cytotoxic activity, leading to tumor growth and metastasis." (PMID 39364312, 2024). "Here, we provide a new mouse model and evidence that Tgfbr2 downregulation promotes ICC formation, indicating that Tgfbr2 is a potent tumor suppressor of ICC." (PMID 38212325, 2024). "To answer that question, we screened the pan-cancer database of the kmplot.com database and selected those neoplasias where at least one member of the overexpression of TGFB2 or TGB3 and TGFBR2 or TGBR3 negatively affected the overall survival." (PMID 38196068, 2024). "To test the relative importance of the STAT3 and TGF-β pathways to tumor morphology and functionality, we generated STAT3/SMAD4 and STAT3/TGFBR2 double knockout (DKO) cell lines." (PMID 38573819, 2024).
tumor (continued). "A tendency towards the upregulation of several known suppressors of anti-tumor immunity and initiators of epithelial-mesenchymal transition (EMT) was observed: TGFBR1, TGFBR2, TGFB3 and TPT1." (PMID 37033948, 2023). "Spatial CRISPR screening confirmed tumor-facilitating effects of immune checkpoints (PD-L1 and CD47), and also identifies tumor composition, organization, and immune infiltration in the TME, following Socs1 and TGFBR2 KO lesion." (PMID 36797756, 2023). "In Cluster2, the up-regulated gene sets included growth receptors such as EGFR, TGFBR2, and GHR, as well as tumor suppressor genes found in apoptotic gene sets." (PMID 37226243, 2023). "The IHC results of xenografted tumor showed that USP33 depletion inhibited the expression of Ki67, PCNA, TGFBR2 and ZEB1." (PMID 37322017, 2023). "EWSR1-FLI1 uses a specific enzyme, named lysine-specific demethylase 1 (LSD1) to repress some critical tumor suppressors, such as lectin-like oxidized low-density lipoprotein (LDL) receptor-1 (LOX1) and transforming growth factor beta receptor 2 (TGFBR2)." (PMID 36979853, 2023). "Furthermore, TGFBR2 deficiency in HCT 116 cells leads to the down-regulation of miR-381-3p, which is expected to be of functional relevance and may contribute to MSI-specific tumor characteristics." (PMID 35465317, 2022). "For instance, downregulation of miR-301a was shown to inhibit CRC migration and invasion both in vitro and in vivo by repressing TGFBR2 protein expression in an analysis containing 48 cases of CRC tissues, adjacent non-tumor tissues and five CRC cell lines." (PMID 36430910, 2022). "Taken together, these findings indicate that high expression of TGFBR2 in SCLC‐dominant NK cells can impair their cytotoxic activity, favoring tumor growth and metastasis." (PMID 36618022, 2022). "It has been shown that miR-200b stimulates tumour growth by targeting and negatively regulating CDKN1B, a negative regulator of the cell cycle, in TGFBR2-null CRC cell lines." (PMID 36140249, 2022). "The expression of the TGFBR2(p = 0.001), PPP1R12B(p = 0.010) were downregulated in tumor tissues, while the expressions of miR-17-5(p < 0.000) were upregulated in tumor tissues." (PMID 35241117, 2022). "In another approach, when TGFBR2 is depleted in CD4+ T cells, a remodeling of the vasculature in the tumor leads to the death of tumoral avascular regions and suppresses the tumor progression." (PMID 35565420, 2022). "The PPI network analysis with cancer-related terms defined six proteins: TGFBR2, TGF-alpha, FGF21, SMAD4, TGFBR1, and FZD3, most of which are involved in tumor development." (PMID 35999337, 2022). "MiR-21, miR-135b, and miR-301a exert their tumor-promoting role in proliferation, migration, and invasion in CRC cells by targeting TGFBR2." (PMID 35465317, 2022). "TGFBR2 incactivation in tumor-initiating hepatocytes (TICs) was found to promote HCC progression, also suggesting a tumor-suppression role for TGF-β in TICs." (PMID 36467404, 2022). "The regulation pair of miR-17-5p and TGFBR2 has a specific correlation with TMB and tumor microenvironment but has nothing to do with DNA methylation." (PMID 35241117, 2022). "Conversely, an anti-angiogenic role was identified in CRC where miR-17-92 downregulated angiogenic inducing genes: TGFBR2, HIF1α, and VEGFA, and a tumor suppressive role was identified in prostate cancer." (PMID 33572600, 2021). "TGFBR2, namely TGF-β type II receptor, belongs to a member of the TGF-β signaling, which is involved in tumorigenesis and tumor procession." (PMID 34906151, 2021). "The size of the tumor also affected the expression of BMP3 (P = 0.0047), BMP7 (P = 0.0210), BMPR1B (P = 0.0460), ACVR2A (P = 0.0350), ACVRL1 (P = 0.0045), TGFBR2 (P = 0.0170), and TGFBR3 (P = 0.0150) according to the K-W test." (PMID 34036102, 2021).
tumor (continued). "Next, we evaluated the specific promoter methylation of the four genes from the TGFβ signaling pathway (TGFBR2, SMAD4, SMAD7 and SNAI1) evaluated in SNU449 cells in resected human HCC tumors, as well as in the surrounding non-tumor tissues." (PMID 34571856, 2021). "More importantly, TGFBR2 knockdown inhibited the stemness of both A549-Teton-shMYOCD to a similar degree as LY2109761 did in SFA in vitro and tumor formation assays in vivo." (PMID 33995678, 2021). "EMP3 expression was found to be correlated with the activation of TGF-β/Smad2/3 signaling by interaction with TGFBR2, which resulted in TGF-β stimulated gene expression and tumor cell proliferation." (PMID 32857809, 2020). "TGFBR2 knockout enhances the antitumor efficacy of CAR T cells in vivo in cell line–derived xenograft and patient tumor–derived xenograft (PDX) mesothelin pancreatic carcinoma." (PMID 33117361, 2020). "TGFBR2, as a member of TGF-β/Smad signal pathway, is an important tumor suppressor, which mediates TGF-β signaling and induces cell cycle arrest and apoptosis." (PMID 32046777, 2020). "Tumor tissue expression of proteins AFP, TGFBR2, pSMAD2, E-cadherin, PIVKAII, cMET and Glypican-3 was analysed to determine relationship to clinical outcomes in Part A or Part B, separately or combined." (PMID 32210440, 2020). "In addition, the data from this current study supports the speculation that upregulated lncRNA MBNL1-AS1 or inhibited miR-301b-3p suppresses CSC proliferation, invasion, migration, drug resistance, sphere formation, and tumor formation in NSCLC by upregulating TGFBR2." (PMID 31113460, 2019). "It exercises its role as a tumor suppressor by negatively regulating the expression of target genes such as PTEN, TGFBR2, ZBTB4 and SMAD4." (PMID 31200745, 2019). "Further experiments demonstrated that the MYEOV ceRNA sequestered miR-30c-2-3p from binding its targets TGFBR2 and USP15 mRNAs, which in turn leading to constitutive activation of TGF-β signaling and tumor progression in NSCLC." (PMID 30181549, 2019). "We then explored the role of miR-655 in PC cells, which demonstrated the tumor suppressive role of miR-665 via targeting TGFBR1 and TGFBR2 by regulating SMAD2/SMAD3 pathway." (PMID 29899418, 2018). "Intriguingly, some of these molecules are related to oncogenesis and tumour progression/metastasis, namely, HRAS, KRAS, TGFBR1, TGFBR2, RB1, ITGA6, ITGB4, mTOR, TSC2 and APLP2." (PMID 30258067, 2018). "This study identifies new tumor suppressor genes, LRP1B and TRAF3, with possible interactions with HPV and confirmed the role of TGFBR2 and PTEN in ASCC carcinogenesis." (PMID 29804324, 2018). "In vitro analyses have shown a tumor suppressor role of miR-145, where miR-145 inhibits TGF-β-induced epithelial-mesenchymal transition and invasion through the repression of SMAD3 and TGFBR2 in NSCLC cells." (PMID 28915579, 2017). "We also compared our Tgfbr2 cKO anorectal SCC CD34+ CSC gene signature with DMBA-induced skin SCC CD34+ cells with overexpression of VEGF, which accelerates tumor growth." (PMID 28219480, 2017). "TGFBR3 can act as a tumor suppressor, which acts negatively on TGF-β signaling by binding to TGFBR1 and TGFBR2 separately, thereby inhibiting the TGFBR1/2 complex formation." (PMID 29084941, 2017). "ACVR2A, TGFBR2, KIAA2018, ASTE1 and SLC22A9 frequently harbour MSI events in STAD and COAD, whereas several other genes are mostly specific to a single tumour type." (PMID 28585546, 2017). "The most recurrent frameshift MSI events are found in ACVR2A (51.6% of the tumours), KIAA2018 (51%), SLC22A9 (50%), ASTE1 (45%), TGFBR2 (44%), NDUFC2 (36%), LTN1 (36%) and SEC31A (36%)." (PMID 28585546, 2017). "Pathological grading, TGFBR2, TGF-β, MAPK, pin1, β-catenin in tumor tissue and TGF-β in normal mucosa were ultimately identified as significant prognostic predictors." (PMID 27008710, 2016).
tumor (continued). "In xenograft tumors formed with SAHA-treated H460 H-INV cells, we detected increased density of staining for TGFBR2 and MEF2C in overall tumor cells." (PMID 27634890, 2016). "The TGF-β signaling pathway acts as a tumor-suppressor during the early stage of CRC, which is often inactivated via the downregulation of TGFBR2." (PMID 26061281, 2015). "We demonstrated that miR-135b exerted a tumor-promoting effect by inducing the proliferation and inhibiting the apoptosis of CRC cells via the negative regulation of TGFBR2 expression." (PMID 26061281, 2015). "In mice administered adenoviruses expressing either TGFBR2 or EXT1, tumor growth suppression by IFN-α/5-FU was significantly enhanced compared with that in controls." (PMID 23457527, 2013). "In terms of time-scale analysis the consequences of short-term and long-term TGFBR2 expression and signaling on the glycobiology in MSI tumor cells can be easily determined." (PMID 23468914, 2013). "TGFBR2, SMAD3, SMAD5, SOS1 and SOS2 were found to be lower expressed in VEGFA165 tumours compared with control tumours." (PMID 22045186, 2011). "Notable, genes involved in TGF-β signalling (SOS1, SOS2, SMAD5, LTBP3, TGFBR2, IRF7 and CREBZF) were found to be significantly (P<0.01) downregulated in the VEGFA165 tumours." (PMID 22045186, 2011). "Thus, inactivation of TGFBR2 or BAX may contribute to tumor progression." (PMID 21949851, 2011). "Some genes, such as MIF and CCDN2, bore predominant pro-tumor progression functions, other genes, such as KLF5 and TGFBR2, contribute to tumor suppression functions." (PMID 18570662, 2008). "The network includes genes that are cancer promoters and tumor suppressors such as FYN HSPA8, YWHAZ, LEPR and TGFBR2, IRF2, EP3000 respectively." (PMID 18811983, 2008). "In summary, miRNAs can target and regulate TGFBR2, HIF1α, and VEGFA to inhibit tumor angiogenesis." (PMID 39857292, 2025). "Biomarkers such as tumor-infiltrating lymphocytes in the tumor immune microenvironment (TIME), programmed death-1 ligand (PD-L1) expression, KRAS alteration, and TGFBR2 may predict the efficacy of pharmacotherapy including ICIs for biliary tract cancer." (PMID 40647383, 2025). "Notably, CAF-FAP and CAF-C7 both showed upregulated chemokine signaling pathway, but showed high expression of pro-inflammatory genes (CCL2, CXCL12, GDF15, and LIFR) at tumor core and pro-fibrotic genes (TNFRSF12A, TGFBR1, TGFBR2) at FR, respectively." (PMID 39870619, 2025). "As expected, knockout (KO) of Nf1 or Tsc1 or Tgfbr2, but not Nf2, increased the number of spontaneous lung metastatic nodules and increased the primary tumor size." (PMID 38997291, 2024). "In GBM, ERBB3, IGFR1R and TGFBR2 were positively correlated with PDGFR, and combining a PDGFR inhibitor with either an ERBB3 inhibitor or an IGF1R inhibitor resulted in a more significant reduction in tumour growth than each inhibitor alone." (PMID 39272879, 2024). "TGFBR2, a central component of the TGF-β pathway, is often deleted during carcinogenesis in numerous cancer types, including NSCLC, and functions as an effective tumor suppressor in NSCLC." (PMID 39712244, 2024). "We further analysed the correlation between CXCL12, CD44v6, HIF1A, TGFBR2 and KRT7 expression in metastatic tumor tissues & exosomes with sex, age, habit, Tumor Differentiation grade, TNM stage, EGFR mutation status, AE1, Chromogranin, CDX2, CEA, CK20, TTF-1 & CK7." (PMID 38877052, 2024). "Many studies have reported the suppressive function of TGFBR2 in tumorigenesis, but no previous report has been able to highlight its regulatory role in governing the tumor texture and morphology." (PMID 36902378, 2023). "We observed significant inhibition of tumor growth, as well as increased infiltration of T cells, in ADAM12-tTA-CreTgfbr2 mice compared with WT littermate mice, showing that TGFBR2 is required for the pro-tumorigenic role of ADAM12+ cells." (PMID 37798557, 2023).
tumor (continued). "A preclinical study showed that treatment of glioblastoma stem cell-engrafted mice, with allogeneic NK cells in combination with inhibitors of integrin or TGF-β signaling or with TGFBR2 gene-edited allogeneic NK cells, prevented GSC-induced NK cell dysfunction and tumor growth." (PMID 36792722, 2023). "Moreover, TrkC significantly inhibited tumor suppressor activity of TGF-β through reduction of the mRNA expression of one of its receptors, TGFBR2 via TrkC-induced stabilization of EWSR1-FLI1." (PMID 36171207, 2022). "In summary, we have identified a miRNA-mRNA regulatory pair (miR-17-5p and TGFBR2) that may be involved in the pathogenesis of BLCA and played an important role in disease diagnosis, tumor immunity, and other clinical applications." (PMID 35241117, 2022). "In addition, conditional knockout mice with Tgfbr2 deletion in myeloid cells are resistant to tumor metastasis as a result of MDSC dysfunction, implying a critical role of TGF-β in MDSCs during tumor metastasis." (PMID 35720407, 2022). "These miRNAs are important negative regulators of the expression of tumor suppressor genes such as PTEN (phosphatase and tensin-like protein), TGFBR2 (transforming growth factor beta receptor 2), SMAD4 (mothers against decapentaplegic homolog 4), and p21 (cyclin-dependent kinase 2 inhibitor)." (PMID 35205839, 2022). "ADAMTS9-AS1 could sequester miR-301b-3p to mediate TGFBR2 protein, thereby affecting the JAK STAT signaling, and repressing tumor progression." (PMID 34900984, 2021). "Additionally, genomic changes impairing TGFBR2 promote oncogenesis and stabilize EBV infection in tumor cells." (PMID 34234122, 2021). "Co-culture studies of tumour cells with pre-osteoblastic cells show that osteoblasts reduced the proliferation of tumour cells, which can be regulated by low expression of Axl via targeting of TGF-β and TGFBR2." (PMID 34975909, 2021). "Interestingly, in PDCD1-TGFBR2 DKO CAR T-cells, tumor eradication was more efficient in comparison to TGFBR2-edited CAR T-cells, emphasizing the importance of synergizing the knockout of multiple T-cell inhibitory pathways." (PMID 34446084, 2021). "In the small tumor lesions of the Tgfbr2 knockout mice, the numbers of αSMA-positive cells were not increased in the stroma, and Ki67 staining efficiency of tumor cells was lower than that in No-Tam control mouse tumors." (PMID 33558489, 2021). "Simultaneously, the tumor-suppressor genes p21, PTEN, and TGFBR2 were upregulated." (PMID 33456583, 2021). "The antibody against TGFBR2 did not pass the quality control check in the tumor samples due to non-specific staining and thus, was not further analyzed." (PMID 32913559, 2020). "In further agreement, other studies have shown that the anti-tumour effect of TGF-β1 is associated with TGFBR2 activity and is mediated by regulating the cytotoxicity of NK cells, as tumours grow irrespective of TGFBR2 inhibition in mice that lack NK cells." (PMID 33114183, 2020). "TGFBR2 is a key receptor in mediating the tumour growth factor‐beta signal propagation, and knockdown of TGFBR2 was effective in suppressing GBM invasion via a tumour growth factor‐beta‐dependent manner." (PMID 32319715, 2020). "Our study confirmed that TGFBR2 expression was highly suppressed in ESCC cells and tumor tissues." (PMID 32046777, 2020). "Independent of its protein-coding capacity, MYEOV transcript exerts its pro-metastatic function via abrogating the suppression of TGFBR2 and Ubiquitin specific protease 15 (USP15) expression by miR-30c-2-3p, leading to constitutive activation of TGF-β signaling and tumor progression in NSCLC." (PMID 30181549, 2019). "In the absence of dox, these cells are TGFBR2-deficient (−dox, dT), which mimics the condition of most primary MSI tumors that have lost receptor expression during tumor progression." (PMID 31454892, 2019).